IFNG (interferon gamma)
Diseases named in the same sentence as IFNG in open-access papers (continued):
Sharing a sentence is not in itself a finding about the gene and the disease.
tumor (continued). "However, MAIT cells from HCC tumours showed reduced IFNγ and IL-17 production but did upregulate the pro angiogenic cytokine IL-8, again suggesting a pro-tumour role." (PMID 33808058, 2021). "NK/DC signaling can occur via Flt3L, IFNγ and TNFα and may be a crucial factor in augmenting cross-priming and anti-tumor responses." (PMID 34552594, 2021). "The authors found that intrathecal administration of B-cell depleting anti-CD20 antibodies resulted in significantly longer survival than the IgG control and this was accompanied by an increase in tumor-infiltrating granzyme B and IFNγ-expressing effector CD8+ T-cells." (PMID 34483843, 2021). "It was revealed that the main enriched pathways in the tumor, including epithelial-mesenchymal transformation, hypoxia, inflammatory Response, interferon-gamma response, and NFkB-mediated TNFα signal transduction were closely related to the function of CAFs." (PMID 34778248, 2021). "Meanwhile, ferroptosis could also mediate the tumor suppression activity of interferon γ (IFNγ) released by CD8+ T cells." (PMID 34796174, 2021). "Importantly, a significant increase in IFNγ expression was observed on these tumor-infiltrating CD8+ T cells as compared to the vehicle treated tumors." (PMID 34336705, 2021). "In a mesothelioma model, pretreatment of tumors with cisplatin increased gene expression of IFNγ and granzyme B, which could be further increased by subsequent α-GalCer administration, resulting in increased tumor regression." (PMID 34680322, 2021). "In addition to increased antigenicity, IFNγ induces tumor cell death using several direct mechanisms." (PMID 33801234, 2021). "This information is important in that it is known that, although cytotoxic activity is the major function of NK cells, IFNγ production also plays an important role in determining the effector functions as IFNγ exerts antiproliferative and proapoptotic effects on tumor cells." (PMID 33808051, 2021). "IFNγ was the strongest inducer of PD-L1 expression in tumor microenvironment." (PMID 34365463, 2021). "Hence, the same IFNγ signaling processes that promote anti-tumor immunity can achieve the opposite effect by inducing feedback inhibition and tumor immune escape." (PMID 35003017, 2021). "Acetate supplementation ex vivo also increased IFNγ production by tumor-infiltrating lymphocytes." (PMID 33679780, 2021). "Thus, our findings show that the majority of CRC exhibits an activated functional caspase-1/IL-18 axis in tumor cells, and that IL-18 is able to modulate the IFNγ response of TILs in vitro." (PMID 33430344, 2021). "Furthermore, depletion of STAT1 in tumor cells disrupts the IFNγ-mediated SLC7A11 suppression and reverses RSL3-induced ferroptosis." (PMID 34796174, 2021). "In the orthotopic 4T1 mouse model, intratumoral administration of SFV/IFNg virus particles alone or in combination with the Pam3CSK4 TLR2/1 ligand led to significant inhibition of tumor growth compared to the administration of the control SFV/Luc virus particles." (PMID 34835178, 2021). "Furthermore, we detected 11 immune escape genes that were significantly increased by IFNγ, suggesting that these are involved in the formation of an immunosuppressive tumor microenvironment counteracting the inflammatory effect of IFNγ." (PMID 35003017, 2021). "Furthermore, STAT5 overexpression downregulates STAT4 and SATB1 expression through the induction of microRNA-155 (miR-155), empowering tumor immune response escape mechanisms and decreasing the secretion of anti-tumor molecules, such as IFNγ." (PMID 34685762, 2021). "The blocking of CXCL10 and IFNγ was able to slightly reduce the anti-tumor effect of CD20-TCB, suggesting that their inhibition might be able to at least partially block T cell recruitment to the tumor." (PMID 33406104, 2021).
tumor (continued). "Interestingly, similar results were previously reported demonstrating that TIM-3 expression was downregulated on NK cells exposed to tumor targets, and this downregulation correlated with lower cytotoxicity and interferon gamma (IFN-γ) production." (PMID 34069127, 2021). "This supports the hypothesis that SHP2 may enhance resistance of tumor cells to immune-mediated killing via negatively regulating IFNγ signaling, and that SHP2 blockade may function to release this inhibition." (PMID 33446805, 2021). "Interestingly, VEGFR-2 blockade predominantly upregulated PD-L1 expression in HCC cells and increased the PD-1 expression in tumor-infiltrating CD4+ T cells via interferon-gamma of the endothelial cells paracrine." (PMID 34899747, 2021). "Furthermore, IFNγ can exert anti-proliferative, anti-angiogenic and pro-apoptotic effects on tumour cells directly." (PMID 33597595, 2021). "In another study, Th1-derived IFNγ was shown to increase macrophage-mediated anti-tumor cytotoxic activity by inducing the expression of proteases, granzyme A/B, and NK cell-related genes (e.g., NKG2D) and by promoting CXCL9 and CXCL10 secretion by macrophages." (PMID 33801234, 2021). "IFNγ, in turn, provokes the adaptive upregulation of PD-L1 on nearby tumor cells via NFκB." (PMID 34743724, 2021). "As IFNγ is a central immune signalling molecule that is produced by many immune infiltrates, this provides an explanation for the increased IFNγ-signalling in the more hypoxic tumours." (PMID 34819027, 2021). "We hypothesized that addition of IL-18, which can induce the proliferation of several immune effector cells through inducing IFNγ could synergize with IL-27 to enhance tumor growth control." (PMID 34209203, 2021). "Thus, Treg cells become potent anti-tumor cells, as the transfer of Carma1−/− Treg cells is sufficient to reduce cancer growth in an IFNγ-dependent fashion." (PMID 33572260, 2021). "Increased IFNγ activates macrophages and upregulates PD-L1 by tumor cells." (PMID 34394124, 2021). "IFNg GEP and CD8+ TIL in baseline tumor biopsies were significantly associated with ORR and PFS." (PMID 33757523, 2021). "Indeed, our data demonstrated that Y111 triggered the up-regulated expression of CD107a on the surfaces of Vγ2Vδ2 T cells and selectively provoked their production of IFNγ and TNFα in the presence of PD-L1 expressing tumor cells." (PMID 34040604, 2021). "Indeed, the increased immunogenicity of tumour cells allows for elimination by cytotoxic lymphocytes, which are recruited to the tumour by IFNγ-induced chemokine signalling." (PMID 34885021, 2021). "Furthermore, in an in vivo model of pancreatic cancer, IFNγ treatment was shown to inhibit CXCL8 expression on tumor cells, reducing trafficking of suppressive CXCR2+CD68+ macrophages to the TME, restoring immune activity and response to anti-PD-1 therapy." (PMID 33801234, 2021). "Signaling through CD137 delivers an enhanced tumor-selective cytotoxicity and IFNγ secretion." (PMID 34557197, 2021). "Correlative analysis indicated that day 21 IFNγ serum levels were associated with tumor growth inhibition elicited by combination therapy but not by NHS-rmIL12 monotherapy." (PMID 34446712, 2021). "Furthermore, CD4+ T cells have been shown to mediate direct cytotoxicity against tumor cells through increased production of interferon gamma (IFNγ) and tumor necrosis factor (TNFα in both preclinical models and patient-derived CD4+ T cells." (PMID 33383959, 2020). "Neutralization of IFNγ also abrogated the anti-tumor efficacy of the combination treatment." (PMID 32917858, 2020). "EBI3 has revealed growth-promoting activity in lung cancer and in colorectal cancer, by stimulating cell proliferation, via the gp130/STAT3 axis, and by restraining tumor infiltrating granzyme B+ CTLs and IFNγ+ CTLs, thus, allowing the cancer to escape immune surveillance." (PMID 32143355, 2020).
tumor (continued). "Interferon-gamma produced by activated T cells binds to its receptor on tumor cells and determines STAT1 activation and transcription of IRF1/7 which in turn binds to the CD274 promoter, increases PD-L1 transcription and, ultimately, the expression on tumor cells." (PMID 33114576, 2020). "Autologous Mlh1−/− tumor targets triggered IFNγ secretion of lymphocytes from vaccinated mice." (PMID 33087163, 2020). "However, the lower production of pro-inflammatory cytokine TNFα and IFNγ in CD4+T cells or CD8+T cells in the tumor-bearing mice were significantly reversed by DMM treatment." (PMID 32596169, 2020). "Finally, it should be mentioned that there is a third powerful strategy to locally release therapeutic amounts of TNF and IFNγ, which is the transfer of tumor antigen‐specific T cells that release the cytokines upon antigen encounter." (PMID 31916677, 2020). "These cell types have previously been shown to either promote or hinder anti-tumor immunity depending on their cytokine production profile, with type I NKTs producing IFNγ to recruit NK cells and activate DCs, whereas Type II NKTs produce IL-13 and TGF-β that suppress anti-tumor immunity." (PMID 33339195, 2020). "IFNγ is a multifunctional cytokine that plays a pivotal role in tumor immunity." (PMID 32122338, 2020). "Moreover, in C51 tumor-rejecting mice a statistically significant expansion of spleen IFNγ-secreting CD4+ T helper (TH) type 1 cells and F4/80+ macrophages were observed when compared to both P and E C51-injected control mice." (PMID 32197460, 2020). "However, AdIL-17A-transduction also induced strong organ-specific and time-dependent immune activation indicated by dynamic changes of NK cells, B cells, CD4, and CD8 T cells in peripheral blood, lung, and tumor site, as well as the plasma levels of IFNγ." (PMID 32770025, 2020). "Notably, CD8+ IFNγ+ T cell-mediated anti-tumor response poses one of the mechanisms of action of doxorubicin therapy as demonstrated by us previously and is of critical importance for the anti-PD-L1 immune checkpoint therapy." (PMID 33344239, 2020). "SRS has been proven to synergize anti-PD-1 therapy in orthotopic mouse GBM models, by leading to an increase in the amount of CD8+ T cells expressing interferon gamma (IFNγ) as well as a decrease of tumor-infiltrating T reg cells, when compared with a single treatment with SRS or anti-PD-1 therapy." (PMID 32824974, 2020). "Of note, D1143 augments the tumor-specific adaptive immunity induced by ablative radiation therapy, while reducing host immunosuppressive cell infiltrates in the tumor microenvironment in a TNFα, IFNγ and CD8+ T-cell-dependent manner." (PMID 31978106, 2020). "Analysis of tumor CD8+ T cell responses upon T-cell receptor stimulation demonstrated that EBAT treatment induced the highest proportion of CD8+ T cells producing IFNγ and TNFα, as well as multifunctional IFNγ/TNFα double positive T cells." (PMID 33747894, 2020). "In addition, there was an elevation in the number of tumor specific interferon gamma (IFN-γ)-producing cells after one cycle of the vaccination." (PMID 33392179, 2020). "The tumor numbers in the Lgr5/Arf1/Apc/IFNγ-KO and Lgr5/Arf1/Apc/Rag1-KO also significantly increased in comparison with those in the Lgr5/Arf1/Apc mice (Lgr5/Apc: 99.6 ± 8.9; Lgr5/Arf1/Apc: 41.0 ± 5.6; Lgr5/Arf1/Apc/Rag1-KO: 90.4 ± 11.0; Lgr5/Arf1/Apc/IFNγ-KO: 73.0 ± 9.5)." (PMID 31924786, 2020). "In a preclinical model using HSPC transplanted humanized BRGS mice, Capasso and colleagues established breast cancer and colon cancer PDXs, and showed strong suppressive function of PD-1 blockade that resulted in tumor growth inhibition with increased CD8 IFNγ+ tumor infiltrating T cells." (PMID 33603749, 2020). "Furthermore, significant differences occurred between subgroups 2 and 3 at the level of IFNγ receptor expression on tumors, which rendered tumor cells sensitive to IFNγ." (PMID 32795913, 2020).
tumor (continued). "In addition to sensitizing tumor cells to IFNγ-mediated apoptosis, LIGHT induces tumor vasculature normalization, and drives the formation of high endothelial venules which subsequently encourage generation of tertiary lymphoid structures (TLS)." (PMID 32499782, 2020). "In addition, exogenous IFNγ abolishes PGE2-mediated suppression on naïve CD8 T-cell priming, and overexpression of ICAM-1 by tumor cells re-establishes IFNγ production." (PMID 33271839, 2020). "Moreover, metformin increases the number of CD8+ tumor-infiltrating lymphocytes and also protects them from apoptosis and exhaustion which is characterized by decreased production of IL-2, TNFα, and IFNγ." (PMID 32296640, 2020). "Indeed, there was a strong negative correlation between the frequency of CD8+ T cells secreting IFNγ and tumor size at the end point (r2 = 0.436, p < 0.0001), suggesting that IFNγ+ CD8+ cells confer protective antitumor immunity in our model." (PMID 32983966, 2020). "Short-term expanded tumor-specific CTLs derived from four cancer patients exhibited a high frequency of cells with CpG hypermethylation at the IFNγ promoter, with reduced levels of IFNγ mRNA and protein, as well as diminished T cell cytotoxicity." (PMID 32194559, 2020). "The simulations also indicate that whether the immune system can maintain a high ratio of T effectors to regulatory T cells in the tumor as well as generating a moderate but stable concentration of IFNγ might be crucial to control tumor growth." (PMID 31914948, 2020). "According to other studies, chemotherapy and radiotherapy may mediate the release of interferon gamma (IFN-γ) produced by CD8+ T cells resulting in PD-L1 upregulations in various tumor cells." (PMID 32312286, 2020). "This highlighted the importance of IFNγ in mediating anti-tumor T cell responses." (PMID 32194559, 2020). "The presence of an abundant T cell infiltrate and the expression of an IFNγ-signature, along with the expression of PD-1 and PD-L1, are additional favorable predictors of response to ICBs since they represent indicators of a pre-existing anti-tumor immunity." (PMID 32962159, 2020). "Finally, muscles of wild type and Ager−/− mice were injected with TNFα/IFNγ or S100B in a tumour‐free environment." (PMID 32159297, 2020). "Interferon gamma (IFNG) has been known to regulate tumor immune surveillance and tumorgenesis." (PMID 33194339, 2020). "A possible explanation behind the positive effect of eosinophils is their capacity to recruit cytotoxic T lymphocytes through CCL5, CXCL9, and CXCL10, to induce an anti-tumor phenotype in macrophages through TNFα and IFNγ and to normalize the tumor vasculature." (PMID 32793228, 2020). "Indeed, continual or prolonged exposure to the tumor antigen can induce functional exhaustion of the T cells and tumor-infiltrating TCR-engineered T cells can progressively lose the ability to produce IFNγ and TNFα." (PMID 33425916, 2020). "PD‐1 ligands are induced by interferon gamma found in the proinflammatory tumor microenvironment and cause CD8+ T cells to become anergic, even if they recognize the foreign antigens present on the tumor." (PMID 32530570, 2020). "Interestingly, both CD4+ and CD8+ cells from bcl-2 overexpressing tumor produced lower levels of interferon γ (IFNγ) compared with control ones." (PMID 32269145, 2020). "Altogether, these results suggest that the tumor growth delay induced by the CH and NP-ARV treatments could be associated with a Th1 IFNγ type of immune response." (PMID 32626742, 2020). "Additionally, priming of tumor-associated neutrophils with IFNγ and TNF contributed to alterations in the polarization of neutrophils rendering them from tumor promoters to tumor suppressors." (PMID 33363012, 2020).
tumor (continued). "In this study, we established a novel five‐IFNγ response‐related gene signature that provided a better and increasingly comprehensive understanding of tumor immune landscape, and which demonstrated good performance in predicting outcomes for patients afflicted by SKCM." (PMID 32902917, 2020). "In addition to impaired NK cell cytotoxicity and NK cell-dependent tumor surveillance, NK cells from Stat1–/– mice show reduced production of IFNγ in response to stimulation of the NK cell activating receptors (actRs) NK1.1 and NKp46." (PMID 33042133, 2020). "Moreover, the genetic deletion of CISH, in a mouse model of melanoma, significantly increases CD8+ T cells related cytokines production (IFNγ, TNFα, and IL-2) and anti-tumor reactivity, improving the survival of mice for more than 60 days." (PMID 33287413, 2020). "The presence of inflammatory cytokines, like interferon γ (IFNγ), interleukin-17 (IL-17) or tumor necrosis factor α (TNFα), but also oncogenes or tumor suppressors can activate the NF-κB-dependent pathway leading to PD-L1 upregulation and maintenance of immune checkpoint blockade." (PMID 32486375, 2020). "This may be explained by the capacity of IL-18 within the tumor to turn “cold” resistant tumors (high macrophages) into “hot” tumors (high CD8+/IFNγ+/PD-1+ T cells)." (PMID 33261061, 2020). "Activated CD8+ T cells release IFNγ inhibiting tumor cell proliferation and angiogenesis." (PMID 32733470, 2020). "CAR macrophages could contribute to shifting the TME towards tumor rejection by releasing inflammatory cytokines such as TNF, IL-6, IFNγ, and IL-12, by promoting T cell recruitment and function, and tumor growth suppression." (PMID 32429316, 2020). "Tumor cells were a source of IFNγ in the co-culture, inducing IDO expression in ECs." (PMID 33072086, 2020). "Since the frequency of T cells recognizing TAAs and neoAgs, detected by IFNγ production, increased during vaccine stimulation, a relevant question was whether such lymphocytes were able to lyse autologous tumor cells." (PMID 32582212, 2020). "We found IFNγ and TNFα, two major cytokines in tumor microenvironment, could induce programmed death-ligand 1 (PD-L1) expression in MSCs." (PMID 32509271, 2020). "It has been reported that checkpoint blockade could induce an increase in the glucose concentration within a progressive tumor mouse model, which correlated with glycolytic capacity in tumor infiltrating lymphocytes and increased IFNγ production." (PMID 33193345, 2020). "This capacity could favor an increase of the tumor immunogenicity in butyrate-supplemented mice leading to a slight augmentation of IFNγ after ex vivo restimulation." (PMID 32358520, 2020). "From these results, high expression levels of NK cell-activating receptors, activated T cell markers (PD-1, CXCR3, and especially IFNγ), and tumor's T cell recruitment-associated markers (IFNγ receptor, PD-L1, and CXCL9) were necessary for successful T cell infiltration and tumor killing." (PMID 32795913, 2020). "As BED predicts, all three similarly decreased tumor volumes and increased survival times relative to controls, but after high dose exposure in ablative group, the expression of IFNγ was increased following high infiltration of CD8 cells into the tumor microenvironment." (PMID 32287292, 2020). "Efficient anti-tumor immunity also relies on the DC production of IL-12p70, which potentiates Th1 polarization and the capacity of this effector T cell population to secrete Interferon gamma (IFN-γ)." (PMID 32075343, 2020). "Furthermore, the functional blockade of CXCR4 in tumor cells is sufficient to prevent the immunosuppressive ability of MICs by restoring T cell proliferation and IFNγ expression, as well as partially preventing TAM polarization." (PMID 33123122, 2020).